PTPN1 (protein tyrosine phosphatase non-receptor type 1)
Diseases named in the same sentence as PTPN1 in open-access papers (continued):
Sharing a sentence is not in itself a finding about the gene and the disease.
tendinopathy (1 paper, 2025). "However, conditional deletion of Ptpn1 (encoding PTP1B, Ptpn1-/-) in macrophages significantly alleviated tendon inflammation and fibrosis, indicating a strong association between PTP1B and tendinopathy." (PMID 41132674, 2025).
urinary system tumors (1 paper, 2023). "The OS of patients receiving ICI therapy for urinary system tumors in the IMvigor210 cohort with high PTPN1 expression was significantly longer than that of patients with low PTPN1 expression." (PMID 37936713, 2023).
vitiligo (1 paper, 2025). Generalized well circumscribed patches of leukoderma that are generally distributed over symmetric body locations and is due to autoimmune destruction of melanocytes. "Genome-wide association studies (GWAS) have identified approximately 50 vitiligo-susceptibility genes, including PTPN1, PTPN22, NLRP1, FASLG, and TYR." (PMID 40837363, 2025).
cancer (169 papers, 2007 to 2026). A tumor composed of atypical neoplastic, often pleomorphic cells that invade other tissues. "A significant association between PTPN1 expression and overall survival (p < 0.05) wasidentified in 22 of these cancers." (PMID 41432362, 2026). "As the founding member of the protein tyrosine phosphatase (PTP) superfamily, PTP1B (encoded by PTPN1) has been reported to exert critical roles in many physiological and pathological processes, such as insulin signal transduction and cancer development." (PMID 36741874, 2023). "Notably,the prognostic impact of PTPN1 was cancer-type-specific:high expression was associated with improved survival in SARC andCOAD, but with a poorer prognosis in KIRP, LGG, and UVM." (PMID 41432362, 2026). "Moreover, we confirmed that high PTPN1 expression was closely associated with prognosis in most cancers." (PMID 37936713, 2023). "High PTPN1 expression was associated with poor prognosis in most cancers." (PMID 37936713, 2023). "The expressionof PTPN1 was significantly upregulated in tumor tissuescompared to normal tissues in 6 cancer types." (PMID 41432362, 2026). "As PTPN1/2 negatively regulates inflammation and PTPN1/2 inhibition is currently being explored for immunotherapy against cancer, it would be pertinent to assess the impact of PTPN1/2 inhibition on inflammation within the context of DMD and steroid treatment." (PMID 39477543, 2025). "Another five targetable gene dependencies had clinical inhibitors that have reached at least a phase II trial (BIRC2, ITGB1, MAP3K11, LDHA and PTPN1), with 3 having been applied to other cancer types (BIRC2, ITGB1, and LDHA)." (PMID 37997254, 2024). "Evidence for cancer cell-intrinsic roles for PTPN1 and PTPN2 in the development or suppression of tumour growth has emerged." (PMID 38334623, 2024). "We found that PTPN1 expression showed a significant positive correlation with the presence of macrophages in most cancer types." (PMID 37936713, 2023). "The CNV percentage in pan-cancer indicated that heterozygous amplification in cancers were widely found in genes PTPN1, PTPN7, PTPN12 and PTPN14 in most cancers, while heterozygous deletions were widely found in genes PTPN13, PTPN20, PTPN22 and PTPN23." (PMID 37884566, 2023). "The PTPN1 gene is located in the q13.1-q13.2 area of chromosome 20, a region that is gained or amplified in several cancers." (PMID 36735720, 2023). "In this study, we comprehensively investigated the impact of PTPN1 on the prognosis and immunotherapeutic predictive value in human cancers using multiple databases." (PMID 37936713, 2023). "The PTPN1 expression profile was obtained from The Cancer Genome Atlas and Cancer Cell Line Encyclopedia databases." (PMID 37936713, 2023). "To adequately investigate the distribution of PTPN1 expression between cancer and normal tissues, we examined PTPN1 mRNA expression in the 33 cancer types from TCGA." (PMID 37936713, 2023). "The relationships between PTPN1 expression and the presence of tumor-infiltrated immune cells were analyzed using Estimation of Stromal and Immune cells in Malignant Tumor tissues using Expression data and Tumor Immune Estimation Resource." (PMID 37936713, 2023). "Our results showed that PTPN1 was significantly positively correlated with the presence of CD8+ T cells in most cancer types." (PMID 37936713, 2023). "Kaplan-Meier, univariate Cox regression, and time-dependent receiver operating characteristic curve analyses were utilized to clarify the relationship between PTPN1 expression and the prognosis of pan-cancer patients." (PMID 37936713, 2023). "The data showed that PTPN1 was overexpressed in distinct types of cancers, indicating its potential carcinogenic role." (PMID 36741874, 2023). "To summarize, PTPN1 expression varied between immune subtypes and molecular subtypes of various human cancers." (PMID 37936713, 2023).
cancer (continued). "In this study, we performed a comprehensive pan-cancer analysis of PTPN1 expression, integrating several databases (including TCGA, CCLE, TIMER, UALCAN, cBioPortal, and Kaplan-Meier Plotter)." (PMID 37936713, 2023). "Inhibitors of PTPN2 and PTPN1 offer a promising new strategy for cancer immunotherapy and are currently being evaluated in patients with advanced solid tumours (ClinicalTrials.gov identifier NCT04777994)." (PMID 37794185, 2023). "First, the mechanism of PTPN1 alters immune cell infiltration levels in cancers requires further analysis using in vivo or in vitro experiments." (PMID 37936713, 2023). "Patients of each cancer type were divided into two groups based on the best cut-off value for PTPN1 expression: high and low expression." (PMID 37936713, 2023). "Next, Pearson correlation analysis was performed to investigate the relationship between PTPN1 expression and drug sensitivity in cancer cells." (PMID 37936713, 2023). "The results showed that high PTPN1 expression was inversely related to the sensitivity of cancer cells to various chemotherapeutic drugs such as dexrazoxane, paclitaxel, teniposide, eribulin mesylate, perifosine, and denileukin diftitox (Ontak)." (PMID 37936713, 2023). "Univariate Cox regression analyses revealed that PTPN1 expression correlated significantly with OS of patients with six types of cancer, including KICH, LAML, LGG, LIHC, MESO, and UVM." (PMID 37936713, 2023). "Currently, it is widely reported that miRNAs can influence the disease process, especially in cancer, by regulating the expression of PTPN1." (PMID 35957898, 2022). "To evaluate the role of PTP1B (PTPN1) in cancer,we conducted a bioinformatic analysis of 19,131 samples from 34 cancertypes in the The Cancer Genome Atlas (TCGA), Therapeutically ApplicableResearch to Generate Effective Treatments (TARGET) and Genotype-TissueExpression Project (GTEx) cohorts." (PMID 41432362, 2026). "Consistent with the role of the phosphatases in limiting T cell anti-cancer responses, as described using gene knockout models, PTPN1 and PTPN2 inhibitors have been used to enhance anti-tumour immunity and sensitise tumours to other immunotherapy modalities in pre-clinical models." (PMID 38334623, 2024). "This study investigated the relationship between PTPN1 expression and clinical outcomes, immune infiltration, and drug sensitivity in human cancers, which will improve understanding regarding its prognostic value and immunological role in pan-cancer." (PMID 37936713, 2023). "To understand whether PTPN1 was crucial in determining the TME of human cancers, we used the ESTIMATE and TIMER 2.0 databases to examine the relationship between PTPN1 expression and immune cell infiltration in various cancers." (PMID 37936713, 2023). "Collectively, our results suggest that PTPN1 may be a novel promising prognostic biomarker and therapeutic target for pan-cancer patients." (PMID 37936713, 2023). "First, the expression of PTPN1 in different types of cancer was analyzed by the TIMER online tool." (PMID 36741874, 2023). "Therefore, we investigated the potential role of PTPN1 in immunotherapy by examining the relationship between the expression levels of PTPN1 and immune checkpoint-related genes in human cancers." (PMID 37936713, 2023). "However, comprehensive analysis of PTPNs is still missing at the pan-cancer level, especially in AML, and most studies focus on proving the clinical value of PTPN1 expression and PTPN11 mutation in AML14,15." (PMID 37884566, 2023). "Notably, PTPN1, TRIM46, TRIM17, FCGR1A, IRF5, IRF6, and CAMK2B had a higher frequency of gain mutations in most human cancer types." (PMID 37941546, 2023). "Furthermore, the distribution of PTPN1 expression in various cancer cell lines was investigated using the CCLE database, and PTPN1 was found to be widely expressed in almost all types of cancer cell lines." (PMID 37936713, 2023).
cancer (continued). "The pan-cancer analysis revealed that PTPN1 was frequently up-regulated in various cancers." (PMID 37936713, 2023). "In cancer, PTPN1 can act as an oncogene, suggesting that its inhibition may be therapeutically valuable." (PMID 35610725, 2022). "On the other hand, PTP4A1, PTP4A3, PTPN1/PTP1B are overexpressed in various types of cancers." (PMID 32867200, 2020). "Moreover, verifying the significance of the PTPN1/cortactin pathway in cell metastasis of other cancers is needed." (PMID 29743988, 2018). "Next, we investigated whether the observed increase in PTPN1 expression corresponds to increased PTP1B protein levels in colorectal dysplasia and carcinoma." (PMID 26942883, 2016). "Notably, both PRL2 and PTPN1 appeared to be cancer-promoting factors." (PMID 40016288, 2025). "Furthermore, PTPN1 expression correlated highly with the presence of tumor-infiltrating immune cells and the expression of immune checkpoint pathway marker genes in different cancers." (PMID 37936713, 2023). "PTPN1 was overexpressed in multiple cancer types and correlated with the clinical outcome and tumor immunity, suggesting it could be a valuable potential prognostic and immunological biomarker for pan-cancer." (PMID 37936713, 2023). "PTPN1 may play various roles in the prognosis of patients with various types of cancer." (PMID 37936713, 2023). "Furthermore, our results showed that PTPN1 was highly expressed in many cancer cell lines." (PMID 37936713, 2023). "in vitro studies showed that PTPN1 can mediate dephosphorylation of c‐Met and PIK3R2 by binding with both, thereby weakening cell proliferation, metastasis and erlotinib resistance, while CAPN1 could enhance the degradation of PTPN1 protein as a cancer promoter." (PMID 32395869, 2020). "Hence, we postulated that disruption of CTNND1-cortactin interaction may be secondary to curcumin-induced dephosphorylation of cortactin by PTPN1 and may contribute to its effects of curcumin on cancer cell migration." (PMID 24465712, 2014). "For example, PTPN2 (also known as TC-PTP) and its paralogue, PTPN1 (also known as PTP1B), are centrally positioned within cancer development and antitumor immunity, with a wide array of cellular functions attributed to them." (PMID 39065585, 2024). "Collectively, these results suggested a remarkable role for PTPN1 in predicting OS and DSS across multiple cancer types." (PMID 37936713, 2023). "Hence, these results suggest that PTPN1 may be a prognostic factor in different cancer types." (PMID 37936713, 2023). "An orally bioavailable small-molecule active-site inhibitor of the phosphatases PTPN2 and PTPN1, ABBV-CLS-484, demonstrates immunotherapeutic efficacy in mouse models of cancer resistant to PD-1 blockade." (PMID 37794185, 2023). "PTPN1 and PTPN2 have recently become attractive therapeutic targets in the context of cancer immunotherapy." (PMID 37581929, 2023). "In a recent study, a related compound of the PTPN1/PTPN2 inhibitor ABBV-CLS-484, Compound-182, showed promise in small animal models for cancer therapeutics." (PMID 37766318, 2023). "On the other hand, inhibition of negative regulators such as PIAS3, SOCS1 and 3 and several cellular phosphatases (SHP1 and 2, PTPRD, PTPRT, PTPN1 and 2, DUSP22) can also lead to STAT3 activation in cancer." (PMID 35145111, 2022). "A small molecule inhibitor, ABBV-CLS-484, and a related compound-182 inhibit PTPN1/PTPN2 with high selectivity over other phosphatases and mediate anti-tumour effects via direct effects on cancer cells and via the enhancement of NK and T cell recruitment and effector function within tumours." (PMID 38334623, 2024). "PTPN1 and PTPN2 regulate cancer development and responses to immunotherapy." (PMID 38334623, 2024). "Like PTPN2, PTPN1 regulates STAT5-dependent signalling in T cells, whilst the deletion of PTPN1 enhances the efficacy of CD8+ conventional T cell and CAR-T cell ACT in mouse models of cancer." (PMID 38334623, 2024).
cancer (continued). "Protein tyrosine phosphatase non-receptor type 1 (PTPN1), a member of the protein tyrosine phosphatase superfamily, has been identified as an oncogene and therapeutic target in various cancers." (PMID 37936713, 2023). "Subsequently, ROS inhibit the phosphatases PTEN (phosphatase and tensin homolog) and PTP1B (protein tyrosine phosphatase non-receptor type 1), negative regulators of the PI3K/Akt/mTOR and MAPK/ERK mitogenic signaling cascades, thereby driving the survival and proliferation of cancer cells." (PMID 37760037, 2023). "Our findings suggest that PTPN1 has a good predictive value for OS and DSS and may be useful for the prognostic evaluation of patients with multiple types of cancer." (PMID 37936713, 2023). "As mentioned, both mammalian orthologues of PTP61F, PTP1B and TCPTP (encoded by PTPN1 and PTPN2, respectively), have roles in multiple cancers, though not necessarily as tumor suppressors." (PMID 34884538, 2021). "Compared with cells expressing BirA* alone, we identified proteins that potentially associate with PD-L1, and one of them was the protein tyrosine phosphatase PTP1B (also called PTPN1), which is highly correlated with tumorigenesis and progression of various cancers." (PMID 33884962, 2021). "PTPN1 (PTP1B), the founding member of the PTP gene family, is an ubiquitously expressed negative regulator of insulin signaling, and it plays both oncogenic and tumor suppressor roles in human cancer." (PMID 34957126, 2021). "The TISIDB online website was further used to detect the relevance of PTPN1 for multiple immune subtypes (C1: wound healing, C2: IFN-gamma dominant, C3: inflammatory, C4: lymphocyte-depleted, C5: immunologically quiet, and C6: TGF-β dominant) of different cancer types." (PMID 37936713, 2023). "Yet surprisingly, PTPN1 knockout mice do not develop cancers." (PMID 18317580, 2008). "Therefore, we spotted that there is a potential target molecule PTPN1 in CAPN1, which is related to dephosphorylation of manifold RTKs,23, 24, 25 but there is little evidence for the interaction between CAPN1 and PTPN1 in cancer, and the effects of PTPN1 on cancer is still controversial." (PMID 32395869, 2020). "In addition to imprinted genes, the 20q11-q13.32 chromosomal region contains multiple non-imprinted genes involved in cancer, e.g., AIB3, AIB4, AURKA (STK6), BTAK, MYBL2, PTPN1, STK15, and ZNF217." (PMID 36461044, 2022).
tumor (145 papers, 2008 to 2026). "PTPN1/2 are also implicated in breast and prostate cancer and exhibit both tumor-suppressive and tumor-promoting roles." (PMID 39477543, 2025). "Nonetheless, current studies on PTPN1 are limited to a few tumor types, and the prognostic value and immunity-associated role of PTPN1 in human tumors is still elusive and warrants further investigation." (PMID 37936713, 2023). "Hypoxia-induced miR-210 can regulate tumor cell susceptibility to cytolytic T-lymphocyte-mediated lysis by a mechanism involving its downstream targets PTPN1, HOXA1, and TP53I11." (PMID 29872497, 2018). "As loss of either PTPN2 or PTPN1 increased the sensitivity of tumour cells to checkpoint blockade in an in vivo CRISPR screen, and because both phosphatases dampen immune cell activation, we sought to identify a dual PTPN2/N1 inhibitor to further enhance anti-tumour activity." (PMID 37794185, 2023). "Furthermore, AC484 demonstrated additive growth inhibitory effects in Ptpn2-deficient or Ptpn1-deficient B16 tumour cells." (PMID 37794185, 2023). "In the context of tumor immunity, PTPN family members (PTPN6, PTPN3, PTPN2, PTPN1) shape the tumor microenvironment by regulating the development and function of immune cells, thereby influencing tumor progression and the efficacy of immunotherapy." (PMID 40570022, 2025). "Despite exhibiting both tumor suppressing and tumor promoting effects, PTPN1 appears to act predominantly as an oncogene." (PMID 38706600, 2024). "The same research team reported a similar T cell-intrinsic role for PTPN1 in regulating tumour immunity." (PMID 38334623, 2024). "Recent evidence demonstrated that the role of PTPN1 varies with tumor types and can act as both a tumor suppressor and tumor promoter." (PMID 37936713, 2023). "Tumor infiltration of CD8+ T cells was significantly lower in tumors derived from the PTPN1 knocked-down cells than those derived from the control vector cells." (PMID 37936713, 2023). "Genetic deletion of PTPN2 or PTPN1 in T cells can increase T cell proliferation and cytokine production in vitro and prevent tumour outgrowth in vivo." (PMID 37794185, 2023). "The relationship between methylation and expression of genes GSK3B, THBS1, and PTPN1 manifested a positive correlation in most tumour types, whereas this was reversed for genes PPP1R14D." (PMID 37815881, 2023). "The protein tyrosine phosphatases PTPN2 and PTPN1 are central regulators of inflammation, and their genetic deletion in either tumour cells or immune cells promotes anti-tumour immunity." (PMID 37794185, 2023). "Genetic ablation of PTPN2 or PTPN1 in tumour cells augments signal transduction from type I and type II IFNs, increasing downstream effects, including cell growth arrest, increased production of immune cell chemoattractants and increased antigen presentation." (PMID 37794185, 2023). "Consistent with our results showing an additive effect of dual PTPN2/N1 inhibition in tumour cells, AC484 increased the expression of CD69 in PTPN2-deficient or PTPN1-deficient T cells." (PMID 37794185, 2023). "A previous study has shown that targeting PTPN1 can improve T cell-mediated anti-tumor immunity and synergize with PD-1 checkpoint blockade and improve the efficacy of adoptively transferred chimeric antigen receptor (CAR) T cells." (PMID 37936713, 2023). "PTPN1 is elevated in intra-tumor T cells, and knocking it out promotes T cell antitumor activity and chimeric antigen receptor (CAR) T cell efficacy against solid tumors." (PMID 35957898, 2022). "Our findings confirmed that CAPN1/PTPN1 play crucial roles on proliferation, metastasis and erlotinib resistance of LUAD cells as c‐Met/PIK3R2 regulators, and validated the regulatory mechanism of CAPN1 on PTPN1 in tumor model for the first time." (PMID 32395869, 2020).